BRAF (B-Raf proto-oncogene, serine/threonine kinase)
Diseases named in the same sentence as BRAF in open-access papers (continued):
Sharing a sentence is not in itself a finding about the gene and the disease.
melanoma (continued). "In murine syngeneic mutant-Braf melanoma mice without high mutational load, BRAF inhibitor exposure resulted in residual tumors followed by acquisition of resistance as shown by tumor growth." (PMID 31416487, 2019). "The BRAF mutation constitutively activates BRAF and its downstream mitogen-activated protein-kinase (MAPK) pathway, leading to the aberrant proliferation and survival of melanoma cells." (PMID 31817947, 2019). "Thus, AZD5991 can delay acquired resistance to BRAFi or MEKi in BRAF-mutant or NRAS-mutant melanoma cells." (PMID 31727888, 2019). "Interestingly, Haq and collaborators observed that BRAF(V600E) expression in melanomas correlates with decreased expression of oxidative enzymes, diminished mitochondrial number and function, and increased production of lactate." (PMID 30487597, 2019). "Patients with advanced BRAF mutant melanoma who had received BRAF/MEKi, niv/ipi, or aPD‐1 in the front‐line setting were identified from a nationwide database comprising de‐identified patient‐level structured and unstructured data derived from electronic health records." (PMID 31677253, 2019). "Low SOX10 expressing melanoma cells have been shown to adapt to BRAF inhibition." (PMID 31118886, 2019). "To investigate whether blocking BRAFi-induced autophagy–lysosomal activation alters melanoma response to BRAF-targeted therapy, we used TFEBKD A375 cells reconstituted with WT or mutant TFEB." (PMID 30979895, 2019). "The most dramatic example of this is the variable response to BRAF inhibitors across different tumor types, ranging from a high response in BRAF V600E-mutated melanoma to a complete lack of activity of such agents in BRAF V600E-mutated colorectal cancer." (PMID 32010631, 2019). "Magnolol, three derivatives of magnolol and honokiol were initially tested on NRAS‐ and BRAF‐mutant melanoma cells with the aim to identify whether any of the derivatives showed an improved efficacy over the original compound." (PMID 30793515, 2019). "Increased tumor proliferation induced by the secretome was associated most prominently with activation of the AKT pathway, and dual inhibition of the RAF and the PI3K/AKT/mTOR signaling pathways reduced the growth of drug-resistant cells in a BRAF-mutant melanoma model." (PMID 31815659, 2019). "BRAF V600E mutations for example, required for selection of combination BRAF/MEK inhibitors, occur in one-third to one-half of melanomas, but only in 2–4% of non-small cell lung cancer (NSCLC) patients, both of which are on-label FDA approved indications for BRAF/MEK inhibitors." (PMID 31384390, 2019). "Previous studies reporting that BRAF inhibition in melanoma cells induces a proliferative phenotype and metastasis by reactivating the downstream MAPK pathway may also support our hypothesis." (PMID 31387614, 2019). "Therefore, overexpression of TRIM28 or downregulation of TRIM17 reduce the protein level of BCL2A1 and restore sensitivity to B-Raf proto-oncogene, serine/threonine kinase (BRAF)-targeted therapy in melanoma cells that exhibit a survival dependency on BCL2A1." (PMID 30974870, 2019). "If wild-type BRAF melanoma cells are exposed to BRAF inhibitors, the melanoma cells may paradoxically activate the MAPK pathway, causing adverse effects." (PMID 31817947, 2019). "Indeed, a phase I/II clinical trial of for the dual treatment of patients with BRAF-positive advanced melanoma with BKM120, a PI3K inhibitor, and vemurafenib had been initiated, although terminated early due to therapy-related toxicity (NCT01512251)." (PMID 31338332, 2019). "At the cellular level, the exposure of BRAF-mutant melanoma cells to the compound resulted in a marked down-modulation of KIT, which was paralleled by the shutdown of the MAPK and PI3K/AKT signaling pathways, both at the transcriptomic and post-translational levels." (PMID 31635389, 2019).
melanoma (continued). "In other tumor types, such as melanoma, colorectal, and lung cancer, activating BRAF mutations occur mostly in a non-overlapping distribution with other genes that converge on activation of ERK signaling pathways (i.e., KRAS, NRAS, NF1, EGFR)." (PMID 31158244, 2019). "OleA also contributed to the cytotoxic effect of dacarbazine against BRAF melanoma cells." (PMID 31766676, 2019). "We demonstrate that the BRAFV600E–TFEB/ZKSCAN3–autophagy–lysosomal axis represents a key regulatory pathway through which BRAFV600E orchestrates TGF-β signaling and EMT, resulting in tumor progression, metastasis, and resistance to BRAF-targeted therapy in melanoma." (PMID 30979895, 2019). "Thus, TRAIL-induced apoptosis was strongly enhanced, and TRAIL resistance was overcome in melanoma cells by BRAF inhibitors, including vemurafenib approved for melanoma therapy." (PMID 31083589, 2019). "In particular, selective targeting using BRAF inhibitors is effective in most (up to 80%) BRAFV600E mutant melanomas, but the promising results observed in melanoma monotherapy were not reproduced in colorectal cancer patients, with a response rate of approximately 5%." (PMID 31083627, 2019). "It was observed that melanoma could acquire resistance against BRAF inhibitors by altering the pattern of cytokine production." (PMID 30499222, 2019). "Ethnic and geographical differences have also been reported—in a cohort of Black Africans, in which the incidence of melanoma is low and not related to the sun exposure, the prevalence of BRAF mutations was only 8%." (PMID 30934534, 2019). "Moreover, a direct interaction of AHR with the BRAF inhibitor vemurafenib has been described in melanoma cells as well as in T cells and keratinocytes." (PMID 31795255, 2019). "The present study provides the first in vitro observation that tissue factor expressed in melanoma cells may contribute to the modulation of the coagulation state of patients in the treatment with BRAF inhibitors." (PMID 31467489, 2019). "Our results suggest that with the development of new therapeutic possibilities, not only BRAF testing but complex molecular testing of CM may become an integral part of the decision process concerning the treatment of patients with melanoma." (PMID 31745173, 2019). "Furthermore, first-generation BRAF inhibitors approved for adult melanoma have poor blood–brain penetrance and efficient response is only to be expected in tumors with markedly blood–brain barrier breakdown." (PMID 31181803, 2019). "Activation of AHR conveyed melanoma cells with resistance to BRAF inhibitors." (PMID 31795255, 2019). "Moreover, subgroup analyses from multiple BRAF trials have demonstrated particularly beneficial for the more advanced and aggressive melanoma, such as those with elevated LDH level or brain metastasis." (PMID 31762821, 2019). "Therefore, accurate detection of BRAF status and possible genetic heterogeneity is important in managing melanoma." (PMID 31817947, 2019). "In addition, miR‐211‐5p forced expression reduced sensitivity to BRAF inhibitors and decreased its efficiency in melanoma cell lines." (PMID 30499222, 2019). "Therapeutic targeting of SRF/MRTF may have potential to reverse BRAF inhibitor resistance in melanoma patients bearing the oncogenic RAC1P29Smutation." (PMID 31257073, 2019). "Therefore, the combinational use of a natural endogenous hormone (melatonin) and a small molecule inhibitor (vemurafenib) targeting BRAF should be considered as a promising therapeutic strategy to break drug resistance in melanoma treatment." (PMID 30717768, 2019). "We therefore went on to screen the drug effect on a cohort of 30 patient-derived short-term cultures of melanoma cell lines carrying BRAFV600E/K, NRASQ61K/L/R, NF1null, RAC1P129S, RAF1 or BRAF fusion proteins, as well as other mutations identified by exome-capture sequencing." (PMID 31040916, 2019).
melanoma (continued). "This analysis of BRAFi/MEKi combinations for BRAF-mutant melanoma highlights the differences in tolerability and efficacy that may be useful for therapeutic decision making." (PMID 31653096, 2019). "Advanced melanoma BRAF MUT patients receiving the newest combinations of BRAF and MEK inhibitors achieved outcomes similar to those of unselected patients on ipilimumab/nivolumab therapy; however, immunotherapy resulted in more patients remaining progression-free in the long term." (PMID 30925943, 2019). "However, intratumoral molecular heterogeneity in a BRAF-mutant melanoma implies a subpopulation of cells develop drug resistance, while another distinct population with different genetic component continues to grow and progress." (PMID 30642390, 2019). "Neither BRAF mutation testing nor its inhibitor has been widely used in clinical management of melanoma cases in Indonesia." (PMID 31890008, 2019). "Currently MAPK pathway inhibitors, including BRAF inhibitors (vemurafenib, dabrafenib) and MEK inhibitors (trametinib, cobimetinib), are the only mutation-specific, targeted therapies currently approved for melanoma patients." (PMID 30820351, 2019). "To explore possible mechanisms which could explain this phenomenon, we overexpressed NRAS(Q61) in a set of BRAF(V600E) melanoma lines and vice versa." (PMID 30651601, 2019). "Moreover, Ole demonstrated cytotoxic effect in BRAF melanoma cells and increased the cytotoxic effect of Dacarbazine and Everolimus, conventional drugs used in treatment of melanoma." (PMID 31137753, 2019). "Indeed, when biochemical analyses were performed on BRAF resistant melanoma cell lines generated in some studies, they revealed MEK/ERK reactivation through RAS, which is the key resistance mechanism in these cells." (PMID 31126017, 2019). "Yet, BRAF mutation status is the only known biomarker of BRAF inhibitor sensitivity and no biomarker exists for BRAF wild-type melanoma patients." (PMID 31253656, 2019). "Thus, BRAFV600E-dependent TFEB phosphorylation and TGF-β activation enhances tumor aggressiveness, as observed in BRAF-mutant melanoma patients." (PMID 30979895, 2019). "Several mechanisms have been described to elucidate the emergence of resistance to MAPK inhibitors in melanoma and there is a crucial need for biomarkers to identify patients who are likely to achieve a better and long-lasting response to BRAF inhibitors therapy." (PMID 30899440, 2019). "Since the BRAF inhibitor vemurafenib has been widely used to treat melanoma we also asked whether depletion of BRN2 could affect cell death induced by this drug." (PMID 30804224, 2019). "To provide advanced insight into the signaling responses that occur following kinase inhibition we have performed quantitative (phospho)-proteomics of human melanoma cells treated with either dabrafenib, a BRAF inhibitor; trametinib, a MEK inhibitor or SCH772984, an ERK inhibitor." (PMID 31350469, 2019). "Although double-wild type (BRAF/NRAS) melanoma cells were the most sensitive to the compound (with IC50 below 400 nM), the BRAFV600 mutant cells included a group of highly responsive and less responsive melanoma cells (IC50 below 400 nM and above 500 nM, respectively)." (PMID 31040916, 2019). "Sorafenib was the first BRAF inhibitor developed and was clinically evaluated in melanomas." (PMID 31426419, 2019). "In these samples, a concomitant mutation in HRAS gene (p.Gly12Asp) was identified, confirming the association between inactivating BRAF mutations and the stimulation of the Raf-MEK-ERK pathway by other effectors, as a mutated RAS protein, in a molecular subtype of melanomas." (PMID 31547467, 2019). "However, so far, only one mucosal melanoma carrying both mutants (BRAF D594E + NRAS G13R) has been described." (PMID 31398831, 2019). "However, the use of vemurafenib in melanomas with wild-type BRAF can act as a stimulator for the MAPK pathway, promoting cell growth and proliferation." (PMID 31652660, 2019).
melanoma (continued). "The zoledronic acid + GSK126 association exerted a strong anti-proliferative effect on BRAF-mutant, NRAS-mutant, and BRAF/NRAS wild-type melanoma cell lines, compared to treatment with single agents, and induced significant apoptosis on BRAF wild-type melanoma cell lines." (PMID 30710146, 2019). "MEK inhibitor monotherapy leads to nondurable responses in patients with BRAF V600E-mutated melanoma." (PMID 31466300, 2019). "We collected baseline tumor samples from 64 melanoma patients at BRAF inhibitor treatment initiation and showed that the presence, prior to treatment, of mRNA over-expression of genes’ subset was significantly associated with improved progression free survival and overall survival." (PMID 30899440, 2019). "Pretreatment tumor biopsies from a total of 213 patients (158 for the training set and 55 for the validation set) treated with BRAF or BRAF/MEK inhibitors within the Italian Melanoma Intergroup were stained with selected immune markers (CD8, CD163, β-catenin, PD-L1, PD-L2)." (PMID 31730502, 2019). "ST6Gal-I has also been identified as part of a BRAF-driven metastatic gene signature in melanoma." (PMID 31610800, 2019). "Similarly, amplification of the PAK (p21-activated kinase) pathway is characteristic of BRAF-wild type melanoma, while in BRAF-mutant melanoma it is responsible for resistance to MAPK-inhibitor treatment." (PMID 30634628, 2019). "However, despite FDA-approved BRAF-targeted therapies for advanced stage melanoma showed a great deal of promise, development of rapid resistance limits their success." (PMID 31780644, 2019). "Also, BRAF inhibition in melanoma cells has been related to an induction of apoptosis as well as to a sensitization for other proapoptotic effectors." (PMID 31083589, 2019). "Similarly, targeted therapy has been found to boost type I IFN signalling that promotes cell cycle arrest and dedifferentiation in BRAF mutant melanoma." (PMID 30850015, 2019). "We then focused on the BRAF and NRAS melanoma driver gene mutations." (PMID 31795494, 2019). "For example, in melanoma it has been proved that BRAF inhibition could have favorable effects in the tumor microenvironment and it becomes more immunogenic." (PMID 31172347, 2019). "A decrease in the expression levels of various glycolytic genes, including GLUT1, GLUT3, and HK2, lactate and ATP production was observed in a panel of BRAF(V600E) melanoma cell lines treated with the BRAF inhibitor vemurafenib as well as in samples from patients undergoing BRAF inhibitor therapy." (PMID 30487597, 2019). "To assess whether LATS1-mediated autophagy repression exerts a general function in various types of cancer therapy, we analyzed vemurafenib-mediated BRAF inhibition (BRAFi) in BRAFV600E-mutant A2058 melanoma cells." (PMID 31848340, 2019). "Thus, we reviewed the BRAF or NRAS mutation status in TCGA-SKCM dataset, and our results showed the prognostic values of the 7-lncRNA signature in melanoma patients with different subtypes." (PMID 31649871, 2019). "Recently, the MEKi trametinib was approved for the treatment of BRAF-mutant melanoma." (PMID 30353166, 2019). "In addition to a major role of GABPA, contribution of MAPK-activated ETS-factors have been reported in BRAF-mutant melanoma and thyroid cancer." (PMID 31391125, 2019). "Mucosal melanomas showed a higher incidence of no mutation (P < .01) and a lower incidence of BRAF mutations (P < .001), as compared to those of cutaneous melanomas." (PMID 31277584, 2019). "Furthermore, when BRAF-mutant melanomas are treated with vemurafenib (a BRAFi), the MITF-PGC1α axis is up-regulated, which leads to increased mitochondrial respiration and scavenging of reactive oxygen species (ROS)." (PMID 30971321, 2019). "Finally, we validated our drug combination predictions through a combination of in silico and experimental approaches, including a drug repurposing candidate involving tretinoin in combination with vemurafenib for BRAF-mutant melanoma." (PMID 30820351, 2019).
melanoma (continued). "However, when evaluated in the superficially spreading melanoma subgroup, BRAF V600E positivity indicated adverse RFS (p = 0.039) and OS (p = 0.012)." (PMID 31039200, 2019). "The most common somatic mutations are activating point mutations in the v-Raf murine sarcoma viral oncogene homolog (BRAF; 35–50% of melanomas) and neuroblastoma RAS viral oncogene homolog (NRAS; 10–25%), as well as loss-of-function mutations affecting neurofibromin 1 (NF1; ~15%)." (PMID 31470659, 2019). "In 2015, pembrolizumab received an expanded first-line indication to include previously untreated advanced melanomas regardless of their BRAF mutation status, following the results of the ‘KEYNOTE-006’ clinical trial." (PMID 30975211, 2019). "Beyond specific mechanistic insight into the MEK inhibitor response in BRAF(V600E) mutant melanoma cells, this study provides a comprehensive genomic resource for future studies to identify potential novel loci for pigmentation and drug resistance in melanocytes and melanoma." (PMID 31399133, 2019). "Therefore, we investigated its effect on the growth of a BRAF-mutant xenograft model established from the human melanoma cell line A375." (PMID 31745079, 2019). "In melanoma, acquired resistance to vemurafenib in patients with the BRAF(V600E) mutation was associated with the appearance of BRAF(V600E) splice variants such as those lacking exon cassette 4–8." (PMID 31134126, 2019). "These prompted us to examine whether SOX10 regulates NEDD9 expression in two metastatic melanoma cell lines (A375M and WM266–4) harboring mutated BRAF, which express high levels of SOX10 and NEDD9 expression." (PMID 30642390, 2019). "The overall objective of our studies is to better understand the underlying pathophysiology which could explain the well-established exclusivity between BRAF(V600E) and NRAS(Q61) mutations in melanoma." (PMID 30651601, 2019). "The combination of Wee1 and Chk inhibitors both targeting key enzymes of cell cycle control can kill melanoma cells independent of their BRAF mutation status." (PMID 30728057, 2019). "Therefore, during the progression in melanoma patients with BRAF inhibitors, the expression of melanoma antigens was dramatically decreased along with downregulation of MITF." (PMID 31134073, 2019). "BRAF and NRAS mutations are also key drivers in many melanomas." (PMID 31861163, 2019). "Anaplastic lymphoma kinase (ALK) gene rearrangement testing was performed in patients with adenocarcinoma who were EGFR negative; BRAF was performed in patients with melanoma, and C-MYC mutations in patients with lymphoma." (PMID 31429741, 2019). "Mutant forms of BRAF with reduced kinase activity have been observed in lung tumors and melanoma." (PMID 31581557, 2019). "Our findings increase the awareness of CVAEs in patients with melanoma treated with BRAF and MEK inhibitors and may help to determine the appropriate clinical cardio-oncology management." (PMID 31397860, 2019). "An increased expression of PD-L1 was found in BRAF inhibitor-resistant melanoma cells." (PMID 31258527, 2019). "However, the mitogen-activated protein kinase pathway is activated in most melanoma, including BRAF-wt." (PMID 30428063, 2019). "This scenario is further complicated by the evidence that approximately 10–15% of melanoma patients harboring BRAF-mutations do not respond ab initio to first line therapy, and that 40–50% of patients show only partial responses." (PMID 30254376, 2019). "Due to high GC content of the TERT promoter, and this being a chronologically later mutational hit, we believe BRAF p.V600 and NRAS p.Q61/p.G12 variants to be the best pharmacodynamic biomarkers to monitor treatment response in mutation positive malignant melanoma patients." (PMID 31767937, 2019).